CEP55 (centrosomal protein 55)
Diseases named in the same sentence as CEP55 in open-access papers (continued):
Sharing a sentence is not in itself a finding about the gene and the disease.
cancer (continued). "CEP55 is overexpressed in multiple cancer types and was shown to promote tumorigenesis by upregulating the PI3K/AKT pathway." (PMID 38250876, 2024). "CEP55 belongs to the CIN70 score in cancer patients, and overexpression of CEP55 in mice increased spontaneous tumorigenesis as well as the CIN rate in mouse embryonic fibroblasts (MEFs)." (PMID 39195269, 2024). "Centrosomal Protein 55 (CEP55) is a key regulator of cytokinesis and has been included in a 70-gene chromosomal instability signature associated with aneuploidy in cancer." (PMID 38596293, 2024). "Overexpression of CEP55 has been observed in numerous cancer cell types, including premalignant lesions of the colon, and is a known correlate of poor prognosis." (PMID 39450169, 2024). "The overexpression of CEP55 is significantly correlated with the tumor stage, invasion and metastasis of many malignant tumors." (PMID 38696317, 2024). "To determine if the knockout of CEP55 is sufficient to reduce cancer cell proliferation rate, we tested the cell proliferation ability of CT26 with and without CEP55 expression." (PMID 38250876, 2024). "Consistent with the in vitro data and previous studies on other cancer types, the knockout of CEP55 in CRC impaired tumor progression and reduced tumor size." (PMID 38250876, 2024). "The data of clustered regularly interspaced short palindromic repeats confirmed that CEP55 was essential for the survival of cancer cells in multiple cancer types." (PMID 37173675, 2023). "Findings: CEP55 was aberrantly expressed in most cancers and revealed a prognostic value for several malignancies." (PMID 37484531, 2023). "To assess the relationship between CEP55 expression and pan-cancer prognosis, we estimated overall survival (OS) and disease-specific survival (DSS) using univariate Cox regression with TCGA dataset." (PMID 37484531, 2023). "CEP55 protein expression data for nine of the 20 cancers available from the Clinical Proteomic Tumor Analysis Consortium were collected for this research." (PMID 37173675, 2023). "Overexpression of CEP55 mRNA was a significant predictive and prognostic indicator in various cancers." (PMID 37173675, 2023). "Next, we computed the PCC between CBX2 and CEP55 to validate their positive regulatory relationship across cancers and confirmed that a significantly positive correlation greater than 0.2 was observed in 27/33 cancers, especially in THYM." (PMID 37980163, 2023). "Our findings identify CEP55 expression as a predictor for determining cancer status and indicate a relationship with the prognosis of several cancers." (PMID 37173675, 2023). "In the present study, we investigated CEP55 expression and its relationship with pan-cancer prognoses." (PMID 37484531, 2023). "Among the 21 cancers explored, CEP55 mRNA was overexpressed in 20 cancer tissues (except kidney chromophobe [KICH]) when compared with the respective normal tissues (p < 0.05)." (PMID 37173675, 2023). "The Chronos scores indicated that, CEP55 is essential for various tumors originating from some organs, based on the comprehensive pan-cancer analysis of CEP55 performed in this study." (PMID 37173675, 2023). "We discovered that cancer-associated fibroblast (EPIC, MCPCOUNTER) strongly connected with CBX2 and CEP55, consistently with ECM enrichment." (PMID 37980163, 2023). "The underlying mechanisms of CEP55 in various cancers remain complex; for example, CEP55 expression was correlated with at least five KEGG signaling pathways in six cancers (ACC, etc.)." (PMID 37173675, 2023). "To date, previous studies have investigated the prognosis value of CEP55 expression in some cancers, including ACC, BRCA, GBM, KIRC, LIHC, LUAD, and PAAD." (PMID 37173675, 2023). "Beta-catenin had been confirmed to aggravate hepatocarcinogenesis and promote cancer stem cell properties, which enforced us to explore the relationship between CBX2, CEP55 and cancer stem cells." (PMID 37980163, 2023).
cancer (continued). "CEP55 expression provided the ability to distinguish specific cancer tissues (KICH, etc.)from control tissues with high accuracy." (PMID 37173675, 2023). "We strove to appraise highly efficacious drugs targeting CEP55 therapy, thus further expanding the avenues for targeted cancer therapy." (PMID 37887301, 2023). "Overall, these results exemplify that regulating CEP55 can act as one of the important biological events affecting cancer progression." (PMID 37887301, 2023). "We further investigated the role of DNA methylation, AS, and gene enrichment of CEP55 in the regulation of tumor progression in human cancer." (PMID 37887301, 2023). "The results showed that CCNA2, CDK1, KIF11, MKI67, and PLK1 were significantly and positively correlated with CEP55 in pan-cancer." (PMID 37887301, 2023). "Herein, we comprehensively presented the differential expression of CEP55 in pan-cancer and normal tissues based on large-scale bioinformatics and elucidated its clinical significance." (PMID 37887301, 2023). "With the view that CEP55 is likely to play a vital role in various cancers, an attempt was made to validate the expression and clinical significance of CEP55 in one specific tumor type (i.e., LUSC)." (PMID 37173675, 2023). "CEP55 was identified as an ideal cancer vaccine candidate and a marker for predicting cancer invasion risk, metastasis, and therapeutic outcome." (PMID 37007961, 2023). "According to the TCGA database, Kaplan–Meier curves are useful to show the correlation between CEP55 expression levels and the survival of cancer patients and to assess the prognostic value of differential CEP55 expression." (PMID 37887301, 2023). "The essential roles of CEP55 in multiple cancers were identified using a CRISPR dataset of 1,068 specimens." (PMID 37173675, 2023). "Surprisingly, we performed the differential gene analysis in another 20 cancers and found CBX2 and CEP55 up-regulated in 16 and 18 of 20 cancers." (PMID 37980163, 2023). "For the 21 investigated cancers, the results of the sROC analysis showed that CEP55 expression was highly accurate in identifying 21 types of cancers (sensitivity = 0.91, specificity = 0.93, AUC = 0.97)." (PMID 37173675, 2023). "Initially, we evaluated the expression of CEP55 in several types of cancers and attempted to find the correlation between that and the stage of the examined malignancies." (PMID 37175004, 2023). "In conclusion, our study provides findings that offer a comprehensive assessment of CEP55 and identify the significant clinical value of CEP55 in pan-cancer." (PMID 37173675, 2023). "Overexpression of CEP55 was correlated with the prognosis of cancer individuals for 18 cancer types, exhibiting its prognostic value." (PMID 37173675, 2023). "At the protein level, immunohistochemistry (IHC) data from the HPA database revealed that CEP55 expression was considerably greater in cancer tissues than in normal tissues." (PMID 37484531, 2023). "CEP55 protein levels were higher in cancer tissues than in normal tissues in eight of the nine cancers (except for LUSC) (p < 0.05), and the findings were consistent with the conclusions corroborating the results at the mRNA level." (PMID 37173675, 2023). "In the current study, CEP55 was found to be upregulated in most of the analyzed human cancers versus the corresponding normal tissues, which is considered a traditional feature of oncogenic proteins." (PMID 37175004, 2023). "Given the essential roles and distinct expression levels of CEP55 in a wide range of cancers, the clinical relevance of CEP55 in multiple cancers was further investigated." (PMID 37173675, 2023). "Our results suggest a broad role for CEP55 in the diagnosis, prognosis, and immunotherapy of cancer, providing ideas for a comprehensive understanding of CEP55 in immunotherapy and the development of novel targeted therapies." (PMID 37887301, 2023). "In conclusion, our analysis provides a comprehensive assessment of CEP55 expression in various cancers." (PMID 37484531, 2023).
cancer (continued). "Cancers with high CEP55 levels were considerably enriched in cell cycle- and proliferation-related pathways, such as the mitotic spindle, E2F targets, and G2M checkpoints, indicating that the malignancies were in a high proliferation state." (PMID 37484531, 2023). "Taking LUSC as an example, the results of this study partly verified the expression level and clinical relevance of CEP55 in cancers based on the analysis of internal tissue microarray and multi-center LUSC data (n of samples = 2,956)." (PMID 37173675, 2023). "Cancers with high CEP55 expression showed significantly enhanced cell cycle, proliferation, and immune-related pathways." (PMID 37484531, 2023). "The inclusion of more than just these cancers in our study allowed for an analysis of the prognostic value of CEP55 expression in 33 tumors." (PMID 37173675, 2023). "Next, if CEP55 is used as a prognostic marker for pan-cancer analysis, more mechanisms and regulatory details still need to be explored in depth." (PMID 37887301, 2023). "The clinical value of CEP55 in cancers was assessed using receiver operating characteristic (ROC) curves, Cox regression analysis, and Kaplan-Meier curves." (PMID 37173675, 2023). "Through our pan-cancer analysis, we found that CEP55 was significantly correlated with MDSCs and Th1 cells in most cancers and positively correlated with the expression of checkpoints, such as PD1, CTLA4, LAG3, and TIGIT in certain cancer types." (PMID 37484531, 2023). "CEP55 mRNA expression made it feasible to distinguish 21 cancer types between cancer specimens and their control samples (AUC = 0.97), indicating the potential of CEP55 for predicting cancer status." (PMID 37173675, 2023). "Differential expression of CEP55 is common in cancer, and its elevated expression has been reported several times." (PMID 37173675, 2023). "Next, we analyzed the levels of CEP55 methylation in pan-cancer and its corresponding tissues using TCGA data from the UALCAN database." (PMID 37887301, 2023). "The differential expression and important clinical value of CEP55 have been observed in several cancers, but little is known about the gene in LUSC." (PMID 37173675, 2023). "Overall, the findings from 11,799 samples of various cancers revealed elevated CEP55 expression levels in 20 cancers." (PMID 37173675, 2023). "Sixteen of 21 cancer types had an AUC value of > 0.9 for CEP55 expression, indicating a significant ability of CEP55 expression to distinguish these 16 cancer tissues from their control tissues." (PMID 37173675, 2023). "In conclusion, our study highlights the prognostic value of CEP55 in cancer and further provides a potential target selection for CEP55 as a potential target for intervention in tumor immune infiltration and related immune genes." (PMID 37887301, 2023). "Several studies have investigated the oncogenic roles and effects of CEP55 in individual human tumors; therefore, we directed the current study to analyze the complex behavior of CEP55 in a pan-cancer model." (PMID 37175004, 2023). "The Chronos score reflected the importance of CEP55 in various cancer cell lines, and a value of <0 indicated that decreased expression of CEP55 increased cancer cell death." (PMID 37173675, 2023). "Mechanistically, CEP55 overexpression leads to cancer cell transformation, proliferation, mesenchymal transition, and invasion by directly interacting with the p110 catalytic subunit of PI3K and upregulating the PI3K/AKT pathway." (PMID 37887301, 2023). "To understand the functional role of CEP55 in cancer and to explore the potential mechanisms of related genes in tumorigenesis and progression, we performed functional and pathway enrichment analyses." (PMID 37887301, 2023). "CEP55 was aberrantly expressed in most cancers and showed prognostic value for several malignancies." (PMID 37484531, 2023).
cancer (continued). "CEP55 overexpression significantly affects functional aneuploidy in multiple cancer types, promoting cell cycle progression (CCP) to enhance PRAD cell proliferation and TNBC invasiveness." (PMID 37887301, 2023). "The current study found that CEP55 was upregulated in cancerous tissues versus normal controls where this upregulation was correlated with a poor prognosis in multiple forms of human cancers." (PMID 37175004, 2023). "For example, CEP55 overexpression increases cancer cell stemness and enhances tumor formation by activating the PI3K/AKT pathway." (PMID 35271462, 2022). "In the present study, we found CEP55 upregulation in a large collection of cancer types compared with their normal counterparts, highlighting their association with poor prognosis in cancer patients." (PMID 35517890, 2022). "CEP55 can facilitate the growth, migration, and invasion of cancer cells by activating the PI3K/Akt signaling pathway." (PMID 35549631, 2022). "Here, we propose CEP55 as the considerable target for anticancer drugs and cancer biomarkers because of the massive upregulation and unfavorable clinical features." (PMID 35517890, 2022). "CEP55, overexpressed in glioma tissues and cells, facilitates cancer cell proliferation and suppresses apoptosis through PI3K/Akt/p21 signaling pathway." (PMID 35037833, 2022). "High CEP55 expression is a marker of chromosomal alterations, aneuploidy, and poor prognosis of cancer patients and promotes tumorigenesis in transgenic mice as well." (PMID 35814389, 2022). "This study aimed to provide a comprehensive information about the CEP55 gene, including its expression pattern in several cancer types, conduct functional domain analysis across species, and perform a computational approach for potential inhibitors of CEP55." (PMID 35517890, 2022). "As CEP55 consistently relates to mitotic slippage in certain types of cancers, we urgently need to study the effects of CEP55 reduced expression and if CEP55 plays a central role in the genesis of cytogenetic abnormalities." (PMID 35814389, 2022). "Later, the finding of CEP55 regulatory roles in PI3K/AKT survival signaling illustrated the importance of this protein, especially in cancer where transcriptional upregulation of CEP55 widely contributes to cancer progression." (PMID 34710087, 2021). "Currently, CEP55 has been found to be significantly associated with aggressiveness, TNM stage, and poor survival rate across various cancers, including breast, colorectal, and gastric carcinoma." (PMID 34104194, 2021). "Of note, multiple studies demonstrated that CEP55 had a crucial role in cancer metastasis regulation." (PMID 34055036, 2021). "Growing evidence demonstrates that overexpression of CEP55 and TPX2 have been implicated in the development of the ovarian and numerous other carcinomas." (PMID 35540695, 2021). "Studies have shown that high expression of CEP55 can promote cancer proliferation, migration and invasion." (PMID 32437446, 2020). "Despite Cep55’s crucial role in the division of cancer cells in culture, most embryonic mouse tissues and the adult intestine are formed normally in Cep55-knockout animals." (PMID 32269212, 2020). "Among the cancer driver genes that experienced epigenetic changes in at least five cancer types, we identified eight genes: CEP55, PIF1, RRM2, NCAPH, ZEB2, CIT, FLI1, and PCDH17." (PMID 31900418, 2020). "By constructing the ROC curve, we found that CEP55 can be used as a diagnostic marker for LUAD and LUSC, and people with high expression of CEP55 have a higher risk of cancer." (PMID 32437446, 2020). "In human cancer cell lines, the adaptor protein Cep55 is essential for the MB localization of ALIX and Tsg101, which in turn promote the assembly of the ESCRT-III abscission complex." (PMID 32269212, 2020). "High expression of centrosomal protein CEP55 has been correlated with clinico-pathological parameters across multiple human cancers." (PMID 33087841, 2020).
cancer (continued). "As a cell cycle and proliferation gene, the evidence of CEP55 overexpression promoting tumor progression in many cancers is reasonable." (PMID 32337246, 2020). "The genes CDC20, CDCA8, and CEP55 were prognostic in more than three (multiple) cancer types while other genes were specific for particular cancer types, such as MYEOV for PAAD." (PMID 32489468, 2020). "CEP55 is highly expressed in a variety of cancers, such as breast cancer, prostate cancer, kidney cancer, thyroid cancer, and so on." (PMID 32437446, 2020). "Growing evidence showed that tumor immune environment is related to the prognosis in various cancers; we further explored the correlation between TIICs and CEP55." (PMID 32337246, 2020). "In terms of its mechanistic involvement in cancers, CEP55 increases anchorage‐independent growth, migration, and invasion in vitro and promotes tumor formation in nude mice, possibly through VEGFA‐PI3K/AKT signaling." (PMID 30108112, 2018). "Over the past decade, intensive research has been undertaken to understand the function and molecular mechanism of CEP55 in the context of cancers." (PMID 30096813, 2018). "Although CEP55 is ubiquitously overexpressed in many human cancers, a detailed molecular understanding of its role in tumorigenesis has remained elusive." (PMID 30108112, 2018). "High expression of CEP55 activated prosurvival signaling pathways, resulting in cancer cell proliferation and migration." (PMID 30089483, 2018). "The mechanism of exosomal budding is beyond the scope of this study, further investigations are required to delineate the role of CEP55 in cancer exosomes." (PMID 30008265, 2018). "Taken together, our data suggest that increased sensitivity of CEP55‐knockdown cancer cells to anti‐mitotic agents can be explained by faster entry into mitosis due to premature activation of CDK1." (PMID 30108112, 2018). "First, CEP55 is a cancer–testis antigen, with expression restricted to testis in healthy adults; however, it is re‐expressed in malignant cells in some cancer patients." (PMID 30108112, 2018). "Having established that CEP55‐knockdown cancer cells were more sensitive to anti‐mitotic agents and susceptible to apoptosis, we wanted to determine which of the apoptotic effectors are involved in this response." (PMID 30108112, 2018). "Despite numerous reports demonstrating CEP55 overexpression in cancer, the precise mechanistic link with genomic instability has not been previously investigated and therefore is currently not well defined." (PMID 30108112, 2018). "Given that CEP55 protein was found to be enriched in exosomes from cancer cell lines, we further investigated if this protein was specific to cancer exosomes or non-specifically co-purified with exosomes." (PMID 30008265, 2018). "Like NOL4, CEP55 is also known to be expressed in various cancers, being barely detectable in normal tissues except for testis and thymus." (PMID 28362316, 2017). "Recent studies have indicated overexpression of CEP55 as an important event in patients with certain types of cancer." (PMID 26615423, 2016). "Cancer cell migration and invasion are directly related to metastasis, and CEP55 has been reported to be related to the processes of cell mobility and cancer metastasis." (PMID 26615423, 2016). "CEP55 is one of the centrosome family proteins and functions in cell cycle regulation, which is one of the cancer hallmarks." (PMID 27419373, 2016). "The immunoreactivity of CEP55 was detected at variable levels, and specific CEP55 staining was mostly found in the cytoplasm of carcinoma cells." (PMID 26615423, 2016). "For example, expression of CENPJ, PCM1 and CEP55, which are key centromere proteins, has been observed to promote cell proliferation and migration, and may even modulate treatment response for cancer." (PMID 39565278, 2025). "In cancer biology, CEP55 has gained significant attention in recent years." (PMID 39871389, 2025).